FOXK2 (forkhead box K2)
Diseases named in the same sentence as FOXK2 in open-access papers (continued):
Sharing a sentence is not in itself a finding about the gene and the disease.
ovarian carcinoma (8 papers, 2022 to 2025). A malignant neoplasm originating from the surface ovarian epithelium. "FOXK2 participates in endoplasmic reticulum (ER) stress control to promote the maintenance of stemness and tumor progression in ovarian cancer stem cells (CSCs)." (PMID 38741782, 2024). "FOXA1 and FOXK2 function as oncoproteins in ovarian cancer, while, in contrast, FOXO3a is a tumor suppressor." (PMID 38704607, 2024). "To explore the role of the FOXK2 gene in ovarian cancer, we analyzed its expression in 30 types of pan‐cancer and adjacent non‐tumor tissues using The Cancer Genome Atlas (TCGA) database." (PMID 40212695, 2024). "Our study suggests that FOXK2 is upregulated in the ovarian cancer, which was consistent with existing research results." (PMID 38734828, 2024). "An innovative therapeutic approach leverages the Warburg effect in ovarian cancer, combining forkhead box protein K2 (FOXK2) siRNA and metformin." (PMID 40212695, 2024). "The broad pan‐cancer analysis contextualized these findings, reinforcing the specificity of the role of FOXK2 in ovarian cancer within the larger oncological landscape." (PMID 40212695, 2024). "Our results revealed a significant overexpression of FOXK2 in ovarian cancer tissues, with markedly lower expression in the adjacent non‐tumor tissues." (PMID 40212695, 2024). "FOXA1 has oncogenic activity in ovarian cancer, and FOXK2 was recently identified as a promoter of HGSOC stem cell function." (PMID 38704607, 2024). "Indicating that the phosphorylation site of FOXK2 regulated by PDK2 sustained glycolysis in ovarian cancer." (PMID 38734828, 2024). "This suggests that the IRE1α/XBP1 axis promotes expressions of stemness-related genes, promoting ovarian cancer cell stemness, and that its regulation by FOXK2 is via the IRE1α/XBP1 axis." (PMID 38711526, 2024). "The synergistic effects of FOXK2 silencing and metformin treatment lay the groundwork for innovative treatment modalities in ovarian cancer." (PMID 40212695, 2024). "To further elucidate the functional significance of FOXK2 in ovarian cancer, we silenced its expression in SKOV3 and OVCAR3 cells using siRNA." (PMID 40212695, 2024). "A recent study has found that FOXK2 promotes ovarian cancer stemness by regulating the unfolded protein response pathway, and it regulate glycolysis in adipocyte, but the role of FOXK2 in glycolysis in OC is still unclear." (PMID 38734828, 2024). "Post transfection, we observed a pronounced decrease in cell viability and tumor sphere‐forming ability, reflecting the importance of FOXK2 in ovarian cancer progression." (PMID 40212695, 2024). "We further examined whether phosphorylation of FOXK2 at Ser9, Thr13, and Ser30 enhances ovarian cancer cell proliferation." (PMID 38734828, 2024). "This differential expression pattern indicates that FOXK2 may serve as an oncogene in ovarian cancer and suggests that it could be a potential therapeutic target." (PMID 40212695, 2024). "Building on the initial findings, we extended our investigation to determine the synergistic effect of ZrTCP@siFOXK2 NPs with metformin, given that prior studies confirmed the ability of metformin to enhance the inhibitory effect of FOXK2 siRNA on ovarian cancer cells." (PMID 40212695, 2024). "Collectively, our study illuminates the pivotal role of FOXK2 in the progression of ovarian cancer." (PMID 40212695, 2024). "Additionally, FOXK2 transcriptionally regulates the expression of PDK2, thereby creating a positive feedback loop that sustains glycolysis in ovarian cancer cells." (PMID 40641601, 2025). "In ovarian cancer, the expression of PDK1 and PDK4 were relatively low compared to PDK2, so we haven’t further explored whether they can phosphorylate FOXK2." (PMID 38734828, 2024). "Through comparative chromatin-state and gene expression analyses in ovarian CSCs versus non-CSCs, we identified FOXK2 as a highly expressed stemness-specific transcription factor in ovarian cancer." (PMID 35349489, 2022).
gastric cancer (6 papers, 2019 to 2025). A primary or metastatic malignant neoplasm involving the stomach. "A positive correlation of FOXK2 protein expression with good prognosis has also been observed in gastric cancer, in which FOXK2 levels have been seemingly associated with tumour differentiation." (PMID 30897782, 2019). "Data obtained from the Human Protein Atlas have revealed that gastric cancer patients with high levels of FOXK2 experienced longer Overall Survival (OS) times." (PMID 36172141, 2022). "Clinical data have demonstrated that FOXK2 expression is reduced in gastric cancer tissues, and low FOXK2 expression is indicative of poor prognosis." (PMID 36172141, 2022). "This is consistent with data obtained in gastric cancer cells, where FOXK2 overexpression has been demonstrated to induce early apoptosis and inhibit cell growth, migration and invasion, which is accompanied by an E-cadherin increase and a N-cadherin decrease." (PMID 30897782, 2019). "However, in gastric cancer, their roles diverge: Foxk1 promotes epithelial‐mesenchymal transition, migration and invasion in vitro, while Foxk2 functions antagonistically." (PMID 39789420, 2025). "Interestingly, FoxK1/2 play different roles in gastric cancer, FoxK1 promoting and FoxK2 inhibiting it." (PMID 35903069, 2022). "High-grade gastric cancer tissues express low levels of FoxK2." (PMID 35903069, 2022). "The results showed that high FoxK2 expression predicted a better prognosis, indicating that FoxK2 may be a therapeutic target for gastric cancer and a prognostic milestone for patients with different stages of gastric cancer." (PMID 35903069, 2022).
non-small cell lung carcinoma (6 papers, 2018 to 2024). A group of at least three distinct histological types of lung cancer, including non-small cell squamous cell carcinoma, adenocarcinoma, and large cell carcinoma. "Previous studies proved FOXK2 induced apatinib resistance through VEGFA/VEGFR1 pathway in anaplastic thyroid cancer and mutation of WRN induced apatinib resistance through activating the PI3K/AKT apoptosis-inhibiting pathway in non-small cell lung cancer." (PMID 38402402, 2024). "Additionally, the expression of FOXK2 may be regulated by miR-1271 in non-small-cell lung cancers." (PMID 36172141, 2022).
cervical cancer (5 papers, 2021 to 2025). A primary or metastatic malignant neoplasm involving the cervix. "Consequently, the objective of this study is to elucidate the molecular mechanisms underlying the role of FOXK2 in cervical cancer progression." (PMID 40641601, 2025). "To further investigate the role of FOXK2 in regulating lipid metabolism in a cervical cancer mouse model, we assessed the expression levels of ACC1, FASN, and CPT1A in tumor tissues." (PMID 40641601, 2025). "Our findings indicate that FOXK2 can modulate lipid metabolic reprogramming, thereby promoting the onset and progression of cervical cancer." (PMID 40641601, 2025). "Forkhead box K2 (FOXK2) has emerged as a significant promoter of cervical cancer, signaling its role as an oncogenic factor across various malignancies." (PMID 40641601, 2025). "This study aims to elucidate the lipid metabolism mechanisms by which FOXK2 promotes the progression of cervical cancer." (PMID 40641601, 2025). "In cervical cancer cells, we utilized immunofluorescence experiments and discovered that the knockdown of FOXK2 led to a reduction in the expression level of CPT1A, whereas the expression levels of FASN and ACC1 increased." (PMID 40641601, 2025). "In vitro experiments, our findings demonstrated that FOXK2 enhances the proliferation and invasive capabilities of cervical cancer cells." (PMID 40641601, 2025). "Mechanistically, FOXK2 promotes lipid metabolic reprogramming in cervical cancer by interacting with the mTOR/DRP1 signaling axis." (PMID 40641601, 2025). "Despite these findings, the precise downstream mechanisms through which FOXK2 influences the progression of cervical cancer remain inadequately characterized." (PMID 40641601, 2025). "The results were consistent with those obtained from immunofluorescence assays, reinforcing the conclusion that FOXK2 can influence lipid metabolism in cervical cancer." (PMID 40641601, 2025). "We first established a cervical cancer mouse model and created experimental groups, including the FOXK2 knockout combined with the MP treatment group, and the FOXK2 overexpression combined with the MI treatment group." (PMID 40641601, 2025). "The results demonstrated that FOXK2 is highly expressed in the HeLa cervical cancer cell line, whereas it is expressed at a lower level in SiHa cells." (PMID 40641601, 2025). "Otherwise, circ-ITCH directly binds to miR-93-5p, thus regulating cervical cancer cell metastasis via targeting forkhead box K2 (FOXK2)." (PMID 35327551, 2022). "Based on these findings, to confirm the role of FOXK2 in the progression of cervical cancer." (PMID 40641601, 2025). "In this study, we identified the critical role of FOXK2 in the progression of cervical cancer." (PMID 40641601, 2025). "Furthermore, Transwell assays revealed that FOXK2 markedly promotes the migratory capability of cervical cancer cells." (PMID 40641601, 2025). "Furthermore, the role of FOXK2 in regulating lipid metabolism reprogramming in cervical cancer and its effects on the mTOR/DRP1 axis were validated in xenograft tumor models." (PMID 40641601, 2025). "The findings of this study suggest that FOXK2, along with its associated genes and pathways related to FAO, could serve as promising new targets for the development of novel immunotherapeutics for the treatment of cervical cancer." (PMID 40641601, 2025). "The effects of FOXK2 on cellular proliferation were assessed using CCK-8 and EdU proliferation assays, which demonstrated that FOXK2 significantly enhances the proliferative capacity of cervical cancer cells." (PMID 40641601, 2025).
clear-cell renal cell carcinoma (5 papers, 2019 to 2024). "Contrasting this finding, FOXK2 gene expression has been correlated with poor prognosis and associated with gender and tumour grade in a cohort of clear-cell renal cell carcinoma from The Cancer Genome Atlas (TCGA)." (PMID 30897782, 2019). "In clear-cell renal cell carcinoma, FOXK2 expression was downregulated in tumor tissue, which suppressed the capabilities of proliferation and motility and promoted apoptosis via suppression of epidermal growth factor receptor." (PMID 33313412, 2020). "FOXK2 overexpression significantly induces apoptotic features and inhibits cell growth in both in vitro and in vivo models of clear-cell renal cell carcinoma." (PMID 30897782, 2019). "In the TCGA database, FOXK2 showed decreased expression in tumor samples of glioblastoma multiforme (GBM), renal chromophobe (KICH), and renal clear cell carcinoma (KIRC) compared to the normal control group (p < 0.05) among the 33 cancer types." (PMID 39552461, 2024). "This pattern of differential expression between neoplastic and non-neoplastic tissues has been confirmed in clear-cell renal cell carcinoma patients, in which FOXK2 mRNA and protein levels are downregulated compared to adjacent non-tumour renal tissues." (PMID 30897782, 2019).
anaplastic thyroid cancer (3 papers, 2024 to 2025). "In addition, high FOXK2 expression activates VEGFA, leading to anaplastic thyroid cancer via the VEGFA/VEGFR1 pathway." (PMID 39552461, 2024).
papillary thyroid cancer (3 papers, 2022). "In papillary thyroid cancer, stable knockdown of FOXK2 markedly inhibited cell proliferation, significantly increased the ratio of LC3-II/LC3-I, and reduced p62 expression, whereas overexpression of FOXK2 resulted in the opposite phenotype." (PMID 36172141, 2022). "In the present study, we demonstrated that FOXK2 expression was up-regulated in papillary thyroid carcinoma tissues compared with matched normal tissues." (PMID 35154454, 2022). "In conclusion, we described the molecular mechanism of FOXK2 as an oncogene in papillary thyroid cancer, which promotes cell proliferation and colony formation by inhibiting autophagy." (PMID 35154454, 2022). "In summary, FOXK2 is highly expressed in papillary thyroid cancer and is closely related to its malignant progression." (PMID 35154454, 2022). "In this study, we for the first time reported that FOXK2 plays an important role in papillary thyroid cancer as an oncogene and promotes the malignant progression of tumors." (PMID 35154454, 2022). "In this study, we clarified the expression and clinical significance of FOXK2 in papillary thyroid carcinoma." (PMID 35154454, 2022). "Based on the relative high and low expression of FOXK2 in papillary thyroid cancer cell lines, we constructed RNAi-mediated knockdown PTC cells in BHT-101 and FOXK2-overexpressed cell lines in BCPAP." (PMID 35154454, 2022). "FOXK2 is involved in the development of different types of cancers, however, its function has not been investigated in papillary thyroid cancer." (PMID 35154454, 2022). "However, the expression and biological function of FOXK2 have not been investigated in papillary thyroid carcinoma." (PMID 35154454, 2022).
pulmonary fibrosis (3 papers, 2021 to 2025). Chronic progressive interstitial lung disorder characterized by the replacement of the lung tissue by connective tissue, leading to progressive dyspnea, respiratory failure, or right heart failure. "Targeting circHIPK3/FOXK2 pathway can effectively alleviate TGF-β1 or silica-induced pulmonary fibrosis." (PMID 38741782, 2024). "Recent studies have highlighted FOXK2’s role in metabolic disorders, particularly in promoting glycolysis and contributing to pulmonary fibrosis through the circHIPK3/miR-30a-3p/FOXK2 pathway." (PMID 38741782, 2024). "FOXK2 can promote fibroblast glycolysis and activation, which is also the main driver of pulmonary fibrosis." (PMID 38741782, 2024). "In conclusion, our results identified circHIPK3/miR-30a-3p/FOXK2 regulatory pathway as an important glycolysis cascade in pulmonary fibrosis." (PMID 34239356, 2021). "Recent studies have shown that FOXK2 is involved in aerobic glycolysis regulation as a key transcription factor, however, the relationship between FOXK2 and pulmonary fibrosis is still unknown." (PMID 34239356, 2021). "Further in vitro and in vivo data confirmed that circHIPK3 could dramatically enhance FOXK2 expression by sponging miR-30a-3p, thereby contributing to pulmonary fibrosis progression via regulating fibroblast glycolysis and activation." (PMID 34239356, 2021). "We thus anticipate that strategies surrounding circHIPK3/miR-30a-3p/FOXK2 pathway targeting may represent a new effective therapeutic option to treat pulmonary fibrosis and other fibrotic diseases." (PMID 34239356, 2021). "However, the function of FOXK2 has not, to our knowledge, been reported in pulmonary fibrosis." (PMID 34239356, 2021).
colon cancer (2 papers, 2019 to 2024). "FOXK2-deficient colon cancer cell lines are growth inhibited in both in vitro and in vivo settings." (PMID 30897782, 2019). "FOXK2 has been shown to interact with nuclear Dishevelled (DVL) in colon cancer activating the Wnt/β-catenin signaling pathway." (PMID 30897782, 2019).
esophageal squamous cell carcinoma (2 papers, 2022 to 2024). Esophageal squamous cell carcinoma (ESCC) is a type of esophageal carcinoma (EC) that can affect any part of the esophagus, but is usually located in the upper or middle third. "For instance, miR-602 was thought as a tumor oncogene which could promote cancer cell growth and metastasis by regulating FOXK2 in esophageal squamous cell carcinoma." (PMID 36193504, 2022). "For example, hypomethylation near the promoter of miR-602 can trigger its expression, leading to the inhibition of FOXK2 and subsequently stimulating the proliferation and metastasis in esophageal squamous cell carcinoma (ESCC)." (PMID 38741782, 2024).
Intellectual disability (2 papers, 2019 to 2023). "In human studies, the disruption of FOXK2 was found to be associated with central nervous system abnormalities and intellectual disability." (PMID 36980927, 2023).
liver cancer (2 papers, 2021 to 2022). An epithelial or non-epithelial malignant neoplasm that arises from the liver. "In addition, FOXK2 regulated by miR-1271-5p increased cell proliferation and suggested a poor prognosis of liver cancer." (PMID 35154454, 2022).
Obesity (2 papers, 2017 to 2025). Accumulation of substantial excess body fat. "Moreover, we found that Foxk2 expression levels were induced by obesity in mice iWAT and eWAT (obese db/db mice vs. lean db/m mice)." (PMID 39789420, 2025).
osteoporosis (2 papers, 2025). A condition of reduced bone mass, with decreased cortical thickness and a decrease in the number and size of the trabeculae of cancellous bone (but normal chemical composition), resulting in increased fracture incidence. "Our results suggest that Foxk2 plays a key role in adipocyte differentiation in vitro, and that the Foxk2‐Pparγ axis may serve as a potential therapeutic target in the continuum of aging‐associated or oestrogen lose‐induced bone marrow adipose accumulation and osteoporosis." (PMID 39789420, 2025). "Our study proposes that Foxk2 may serve as a potential therapeutic target for ageing‐associated or oestrogen loss‐induced BMAT accumulation and osteoporosis." (PMID 39789420, 2025). "Given the reciprocal relationship between adipocyte and osteoblast differentiation, Foxk2 is hypothesized to play a key role in ossification and may serve as a therapeutic target for osteoporosis and bone marrow adipose tissue-related conditions." (PMID 40753194, 2025).
ovarian tumors (2 papers, 2022 to 2024). "Recently, it was reported that FOXK2 was upregulated in ovarian CSCs and in human ovarian tumors and implicated in the regulation of the cellular stress response." (PMID 38734828, 2024). "First, we show that the FOXK2 gene is upregulated in ovarian CSCs and in human ovarian tumors and has a critical role in regulating stemness properties, including TIC." (PMID 35349489, 2022). "Additionally, FOXK2 knockdown significantly reduced mRNA expression levels of stemness-associated TFs (SOX2, OCT4, and NANOG) and stemness marker ALDH1A1 in OC cell lines and primary cells dissociated from a human ovarian tumor." (PMID 35349489, 2022).
pancreatic duct adenocarcinoma (2 papers, 2023 to 2024). "Recently, a circRNA derived from FOXK2 (has_circ_0000816) has been found to promote the growth and metastasis of pancreatic ductal adenocarcinoma by sponging miR-942 and directly binding YBX1 and hnRNPK." (PMID 36922872, 2023).
thyroid cancer (2 papers, 2022 to 2024). "More importantly, through TCGA database analysis, we found that the expression of FOXK2 is closely related to the clinicopathological characteristics of thyroid cancer." (PMID 35154454, 2022). "FOXK2 was significantly up-regulated in thyroid cancer tissues compared to normal tissues." (PMID 35154454, 2022). "To explore whether FOXK2 is involved in the malignant process of thyroid cancer, we first analyzed the expression of FOXK2 in thyroid cancer through the TCGA database." (PMID 35154454, 2022). "We obtained ChIP‐seq data of FOXK2 in different cancer species from four datasets: GSE84241(BRCA, MCF‐7), GSE91547(LIHC, HepG2), GSE91647(CML, K562), GSE173780(OV, OVCAR5), and GSE165777(thyroid cancer, CAL‐62)." (PMID 39552461, 2024).
bacterial pneumonia (1 paper, 2024). Acute infection of the lung parenchyma caused by bacteria (e.g., Streptococcus pneumoniae, Haemophilus influenzae, Chlamydia pneumoniae, Mycoplasma pneumoniae, and Legionella pneumophila). "In experimental bacterial pneumonia, Fbxo24 heterozygous mice exhibited preserved mitochondrial function and Foxk2 protein levels compared to WT littermates." (PMID 38735474, 2024).